INS (insulin)
Diseases named in the same sentence as INS in open-access papers (continued):
Sharing a sentence is not in itself a finding about the gene and the disease.
heart failure (continued). "For all outcomes except T2D and progression to insulin, the rate ratios for HFrEF patients were significantly greater than for HFpEF patients, ranging from 1.15 (1.08–1.21, p < 0.001) for all-cause hospitalizations to 1.59 (1.41–1.77, p < 0.001) for heart failure hospitalizations." (PMID 37583714, 2023). "In particular, insulin resistance, a hallmark of T2DM, can also develop from heart failure through oxidative stress dependent on NAD(P)H oxidase, which triggers dysfunction of insulin signalling in skeletal muscle." (PMID 40507126, 2025). "According to the secondary analysis of several clinical trials, insulin therapy increased hospitalization, cardiovascular disease death, and all‐cause mortality for T2DM patients with heart failure." (PMID 41320960, 2025). "The REMIT-DAPA trial found that individuals with T2DM and comorbid heart failure who received a regimen of insulin, dapagliflozin, and metformin had a 2-year remission rate of 38.7%, compared to 21.5% in those treated with insulin and metformin." (PMID 41427055, 2025). "Alterations in cardiac metabolism—such as impaired fatty acid oxidation and myocardial insulin resistance—are recognized contributors to the pathophysiology of heart failure." (PMID 41008649, 2025). "This fuel switch from FAs to glucose poses a significant problem for individuals who are also insulin resistant, which is common in patients with heart failure (HF), characterized by impaired insulin mediated glucose uptake." (PMID 40875150, 2025). "During the study, three patients in the insulin group withdrew due to development of malignant disease (n=2) or heart failure (n=1), while one patient in the dapagliflozin group withdrew due to an adverse event (increased urine output)." (PMID 41282284, 2025). "Three out of the twenty-three patients on insulin therapy who had heart failure were using pioglitazone, a thiazolidinedione agent." (PMID 39295783, 2024). "DPN, heart failure (HF), cerebral stroke, and insulin therapy increased the likelihood of a reduced QoL (EQ-5D-3L < 50)." (PMID 39124656, 2024). "Acute dapagliflozin treatment also increased plasma glucagon concentrations, lowered the insulin-to-glucagon ratio, and increased whole-body glucose turnover in sham-surgery and heart-failure rats." (PMID 39680452, 2024). "The interplay between diabetes and heart failure creates a vicious cycle in which metabolic disturbances promote cardiac dysfunction, while cardiac dysfunction exacerbates insulin resistance and worsens glycemic control." (PMID 39768866, 2024). "Exogenous insulin therapy, which is utilized by all DM1 patients and 1/3rd of DM2 with heart failure patients, has been shown to be a risk factor for incident heart failure." (PMID 39764242, 2024). "Some authors have previously reported contradictory results, suggesting that myocardial glucose metabolism is reduced in heart failure patients compared to normal healthy controls, due to increased insulin resistance in myocytes." (PMID 39202193, 2024). "This is important as cardiac insulin resistance to glucose utilisation in cardiomyocytes contributes to cardiac dysfunction and the development of heart failure." (PMID 38908792, 2024). "HTN, smoking status, heart failure, creatinine, WBC were also risk factors (HR all >1.0; p < 0.05), and PLT, beta blocker, statin, antihypertensive drugs, hypoglycemic agent, and insulin were protective factors (HR all <1.0; p < 0.05)." (PMID 38550515, 2024). "The animal model of IR and heart failure also shows that the activation and conduction changes of insulin signaling pathways in myocardial cells occur during heart failure." (PMID 38523869, 2023). "Sodium-glucose cotransporter inhibitors (SGLT-2i) lower glucose levels independently of insulin while conferring notable benefits for cardiovascular, renal, and heart-failure outcomes." (PMID 38138975, 2023).
heart failure (continued). "In a multivariate logistic regression, factors associated with a higher risk of death were age >65 years, glycaemia >10 mmol/L, CRP and D-dimer level, prehospital insulin and loop diuretic use, presence of heart failure, and chronic kidney disease." (PMID 36844106, 2023). "The adverse impact of insulin production, insulin sensitivity, and pronounced plasma lipid reduction due to statins produces an additional direction in the advent of heart failure and several other cardiovascular events." (PMID 37189744, 2023). "This is because the energy supply for hearts in patients with heart failure is more dependent on glucose oxidation, and insulin resistance in the diabetic population limits the energy supply, which further exacerbates heart failure." (PMID 36670174, 2023). "They regulate blood glucose levels and insulin secretion by antidiabetic agents, control multifactorial risks in cardiovascular abnormalities, and prevent heart failure over time." (PMID 37189744, 2023). "There is a well-known close relationship between dysregulated insulin secretion and heart failure; however, in our cohort, insulin abnormalities were excluded." (PMID 36672887, 2023). "On the other hand, insulin user group had the highest prevalence of cancer, prior myocardial infarction, heart failure, peripheral vascular disease, and CKD (all p <0.001) than the other groups." (PMID 37196125, 2023). "The pathophysiological mechanisms of frailty and heart failure are intertwined, including upregulation of pro-inflammatory states, metabolic impairment, and insulin resistance." (PMID 37875981, 2023). "Among patients starting insulin during hospital stay, nearly 15% were hospitalized for heart failure." (PMID 36767972, 2023). "This hypermetabolic response persists after the burn injury and promotes severe muscle and protein catabolism, insulin resistance, and cardiac insufficiency." (PMID 36700031, 2022). "Prior research has mostly been focused on the endocrine function of the pancreas in patients with heart failure, demonstrating impaired signaling and enhanced insulin clearance." (PMID 35887892, 2022). "The combination of pioglitazone and insulin requires close surveillance for fluid retention and the possible development of decompensated heart failure." (PMID 36295635, 2022). "All together our results demonstrate the importance of early obtaining and maintaining adequate metabolic profile and insulin sensitivity in hypertensive patients in order to possibly limit myocardial damage and progression toward heart failure." (PMID 35966525, 2022). "In patients with low HbA1c levels or more severe forms of heart failure, insulin therapy has been found to be harmful." (PMID 36012897, 2022). "It is well known that insulin resistance and impaired vascular relaxation contribute to cardiac hypertrophy, eventually leading to heart failure." (PMID 36231029, 2022). "Together, these data indicate that combined loss of IR/IGF1R or IRS1/IRS2 signaling in the adult heart results in impaired insulin-mediated signaling, heart failure, and increased mortality." (PMID 36125265, 2022). "MET not only protects type 2 diabetics from CD and heart failure, but it also restores insulin secretion and protects pancreatic cells from lipotoxicity and glucotoxicity." (PMID 34527070, 2021). "Other clinical studies have shown beneficial effects of treatment with glucose-insulin-potassium infusion in post-operative cardiac failure." (PMID 34551626, 2021). "No large scale randomized prospective data are currently available concerning the effects of insulin on clinical outcomes in patients with established heart failure." (PMID 33463901, 2021). "Previous reports have shown that impaired insulin signaling accelerates heart failure via enhancing autophagy." (PMID 34831481, 2021). "Studies have shown that patients with heart failure have similar fasting blood-glucose levels as normal people, but higher plasma insulin levels." (PMID 34285700, 2021).
heart failure (continued). "This evidence suggest that α2M* would have an important role as an insulin sensitizing agent in the heart, as proposed by other studies about patients with metabolic disturbances and heart failure." (PMID 34203120, 2021). "The results showed that HQ-TLZ treatment of heart failure is primarily achieved by regulating the insulin resistance, erbB signaling pathway, PI3K-Akt signaling pathway, and VEGF signaling pathway." (PMID 34285700, 2021). "Insulin use was also a significant predictor of hospitalization for heart failure with HR 2.34 (95% CI 1.19–4.60; P = 0.01) in the fully adjusted model." (PMID 34158057, 2021). "Compared to those without eRVSP data, participants with a valid eRVSP were older, more likely female, leaner, less likely to be insulin-treated and more likely to have renal impairment, atrial fibrillation and heart failure." (PMID 34640520, 2021). "In fact several papers exist on the matter but none have been designed to or contained adequate power in order to analyze the correlation between insulin and the incidence of heart failure." (PMID 33463901, 2021). "Taken together, our findings unveil a novel cardio-protective mechanism that provides new insights into treatment strategies for heart failure by relieving insulin resistance in ischemic myocardium." (PMID 32223896, 2020). "This study showed a 39% decreased incidence rate of hospitalizations for heart failure and all-cause death in patients treated with SGLT-2 inhibitors than those treated with oGLDs or insulin." (PMID 33042651, 2020). "This multinational, randomized clinical trial study had shown a decreased rate of hospitalizations for heart failure and all-cause death in patients with the use of SGLT-2 inhibitors as compared to oGLDs or insulin." (PMID 33042651, 2020). "They had patients with heart failure (54.7%), patients on insulin and CKD which were exclusions for our study." (PMID 32518676, 2020). "Through GSEA analysis, we found that the insulin signaling pathway was negatively correlated with the failing heart expression profiling, suggesting the inactivation of insulin signaling pathway in the development of heart failure." (PMID 32460775, 2020). "mir15a/mir16‐1 protects against pathological cardiac hypertrophy and sequelae (e.g. heart failure) by repressing insulin/IGF1 signaling." (PMID 33377640, 2020). "It exhibits insulin sensitizing properties, and protective effects in Duchenne muscular dystrophy, diastolic dysfunction, tachycardia, heart failure, and atrial fibrillation, and it can fend off cardiotoxic effects." (PMID 31968693, 2020). "Aerobic exercise has favorable effects on lipid metabolism, cardiac remodeling, post-MI heart failure, insulin resistance, and endothelial function." (PMID 31093312, 2019). "Increased lipid accumulation in ectopic tissues, including skeletal muscle and liver, is associated with the pathogenesis of non-alcoholic fatty liver disease, cardiac dysfunction, heart failure, and impaired insulin signaling." (PMID 31399502, 2019). "We conclude that impaired cardiac BCAA catabolism and insulin signaling occur in human heart failure, while enhancing BCAA oxidation can improve cardiac function in the failing mouse heart." (PMID 31277657, 2019). "In heart failure the myocardium becomes insulin resistant which negatively influences cardiac energy metabolism and function, while increasing cardiac insulin signalling improves cardiac function and prevents adverse remodelling in the failing heart." (PMID 30626440, 2019). "Jie Zhao, Shan Luo, and C. Mary Schooling report a Mendelian randomization study of the role of genetically-predicted insulin on myocardial infarction (MI), angina, and heart failure in the UK Biobank." (PMID 31508506, 2019). "All logistic regression models were also adjusted for age, gender, race, body mass index, surgery service, admission glucose, admission creatinine, heart failure, and basal insulin at admission." (PMID 31775749, 2019).
heart failure (continued). "Impairment in insulin signaling and development of insulin resistant myocardium precedes cardiac dysfunction in heart failure and it is a major determine of its progression." (PMID 29928647, 2018). "These temporary changes in the expression of PI3K, Akt, p-Akt, and GLUT4 protein after lipid infusion in this model are consistent with insulin signaling changes at different stages of heart failure." (PMID 30089498, 2018). "The conditional knock-out of IGF1 and insulin in mice that were driven by the creatinine kinase promoter of the muscle only survived for 3 weeks after birth due to cardiomyopathy and subsequent heart failure." (PMID 29484207, 2018). "One school of thought favors a role for insulin therapy in heart failure outcomes, particularly in the elderly." (PMID 29867503, 2018). "Recent evidence suggests cross-talk between inflammation and insulin signaling, highlighting a strong relationship between insulin-resistant states, inflammation, and heart failure." (PMID 30443223, 2018). "The molecular mechanisms of high FFA levels in changed insulin signaling in cardiomyocytes and the pathophysiology of heart failure in insulin-resistant states are incompletely understood." (PMID 30089498, 2018). "During heart failure, which is often accompanied by insulin resistance, metabolic failure of the myocardium and of peripheral tissues has been described in Ref." (PMID 29896157, 2018). "Reduced insulin-dependent glucose uptake follows cardiac insulin resistance, and an impairment of glucose metabolism becomes evident as systolic dysfunction occurs in heart failure." (PMID 28933367, 2017). "A transverse aortic constriction model of heart failure produces cardiac insulin resistance leading to systolic dysfunction and exacerbation of contractile dysfunction." (PMID 27375480, 2016). "At multivariate Cox regression analysis, NT-proBNP was an independent predictor of the outcome of new cancer diagnosis, heart failure or death, along with age and use of acenocumarol and insulin." (PMID 26046344, 2015). "NT-proBNP was an independent predictor of cancer, heart failure, or death (HR=1.038; 95%CI=1.023-1.052; p<0.001) along with age, and use of insulin and acenocumarol." (PMID 26046344, 2015). "We have also described an association between insulin sensitivity and CFR in heart failure patients." (PMID 26613591, 2015). "Of note, up-regulation of inflammatory cytokines, catecholamines and natriuretic peptides in heart failure is known to mediate increased lipolysis and insulin resistance." (PMID 25142635, 2014). "A positive correlation between fasting insulin and plasma and urinary aldosterone levels was demonstrated in patients with class II–IV heart failure included in the ALOFT (Aliskiren Observation of Heart Failure Treatment) study." (PMID 25352918, 2014). "Studies in the canine rapid pacing heart failure model demonstrated a progressive increase in insulin resistance during disease progression." (PMID 21933140, 2011). "In contrast, T2DM patients with cardiac insufficiency had poorer outcomes after insulin use." (PMID 41320960, 2025). "Consistent with a higher comorbidity burden, patients with CHA2DS2-VASc ≥4 also more often received statins, acetylsalicylic acid, metformin and insulin, aligning with prior observations that polypharmacy in heart-failure care tracks with cardiometabolic multimorbidity." (PMID 41257261, 2025). "Both heart failure with preserved ejection fraction (HFpEF) and non-alcoholic fatty liver disease (NAFLD) develop due to metabolic dysregulation, has similar risk factors (e.g., insulin resistance, systemic inflammation) and are unresolved clinical challenges." (PMID 38630423, 2024). "Insulin is associated with worsening heart failure in patients with heart failure with reduced ejection fraction compared to non-insulin treatment." (PMID 39295783, 2024).
heart failure (continued). "As 30% of symptomatic heart failure patients with preserved ejection fraction have normal NT-proBNP levels (< 100 ng/L), it would be of interest to investigate whether low insulin sensitivity could explain a part of this paradox." (PMID 39097697, 2024). "Furthermore, fatty acid binding protein 2 (FABP2) is related to lipid metabolism, whereas the N-terminal prohormone of brain natriuretic peptide (NTproBNP) is a well-known marker of heart failure, but less known for its role in insulin sensitivity." (PMID 38921470, 2024). "Already now, siliсon NPs are applied to deliver chemical preparations for cancer therapy, optimization of delivery of immunostimulating molecules and agents to enhance insulin permeability through the intestinal cells, and for the delivery of atrial natriuretic peptide to treat heart failure." (PMID 39650276, 2024). "However, under pathological conditions, such as type-2 diabetes or heart failure, cardiac insulin signaling is altered." (PMID 39026321, 2024). "Current evidence suggests that insulin can be safely administered to patients with heart failure, and the use of insulin does not lead to an increased risk of heart failure hospitalization, as shown in the ORIGIN and the DEVOTE study." (PMID 38047986, 2024). "The findings indicated that a history of CVD, heart failure, and insulin use may contribute to the relationship between ln (100 × UACR) and MACEs." (PMID 37922304, 2024). "The reduced physiological functions in heart failure patients, such as glucose and insulin transport to skeletal muscle, diffusion through the endothelium, signal transduction processes, and glucose uptake, may contribute to this phenomenon." (PMID 38702735, 2024). "One possible explanation for this observation is that participants who used insulin or had a history of CVD or heart failure may have been more proactive in managing their UACR." (PMID 37922304, 2024). "Therefore, clinical regulation of malonyl-CoA levels is a potential strategy for treating several types of heart diseases, such as heart failure and ischemia/reperfusion, as well as insulin resistance." (PMID 36818560, 2023). "Two miRNAs, miR-21 and miR-92, decreased significantly in heart-failure patients with preserved ejection fraction (HFpEF) after three months of empagliflozin treatment, with no notable differences in patients treated with metformin or insulin." (PMID 37987360, 2023). "The islets used for this dose were only ~85% viable, had what would be considered poor morphology, and came from a donor with heart failure, yet the NIs produced from them were effective in significantly reducing blood glucose levels and the need for insulin long term." (PMID 37616230, 2023). "Notably, our results are consistent with recent reports indicating a clustering of adverse events in diabetic patients on insulin with heart failure at either reduced or preserved ejection fraction." (PMID 35976428, 2023). "Little evidence of directional pleiotropy was found for all models only except for the analyses between short sleep duration and fasting insulin (MR-Egger intercept P value = 0.048) and between long sleep duration and heart failure (MR-Egger intercept P value = 0.029)." (PMID 36277903, 2022). "Similarly, increased apoptosis, altered insulin and adipocytokine signalling have been well established in patients with heart failure." (PMID 35053387, 2022). "Impaired insulin-mediated signaling and heart failure in iCIR2KO and iCIRS12KO hearts." (PMID 36125265, 2022). "Pancreas function/dysfunction in heart failure has received little attention in the literature, which is somewhat surprising since malnutrition and gastrointestinal symptoms are common, as is dysfunctional insulin signaling." (PMID 35887892, 2022). "Overall, the results may imply that the negativeprognostic impact of insulin treatment tends to be prominent in patients with more severely presented heart failure." (PMID 34496864, 2021).